CXCL11 (C-X-C motif chemokine ligand 11)
Diseases named in the same sentence as CXCL11 in open-access papers (continued):
Sharing a sentence is not in itself a finding about the gene and the disease.
tumor (continued). "Tumor-intrinsic T-cell-exclusionary pathways typically converge on a repression of type I and/or II interferons (IFNs), and thence a paucity of IFN-induced T cell chemokines such as CXC-chemokine ligand 9 (CXCL9), CXCL10, and CXCL11 in the TME." (PMID 36531014, 2022). "Although, evidence exists that CXCL12 and CXCL11 exert combined effects during tumor progression, putative interactions are currently not well characterized." (PMID 36539774, 2022). "The present experiments were performed with the human tumor cell lines, A549, DLD-1, and MDA-MB- 231, which we previously characterized for expression as well as their use of CXCR4, CXCR3, and CXCR7 in CXCL12- and CXCL11-dependent chemotaxis." (PMID 36539774, 2022). "We demonstrate that CXCL12 and CXCL11 interact to control migration, invasion, and survival of most, but not of all tumor cells." (PMID 36539774, 2022). "The M1 macrophages produce pro-inflammatory factors (TNF-α, IL-1β, and iNOS), chemokines (CXCL10, CXCL11, and CCL2), antigen-presenting molecules such as MHCII, costimulatory molecules (CD86 and CD80), and antigen-treated peptidases, which play an anti-tumor role in cancer." (PMID 34034714, 2021). "mEHT could support the intratumoral attraction of distantly injected NK-cells, contributed by CXCL11 and MMP2 upregulation, resulting in an additive tumor destruction and growth inhibition." (PMID 33732640, 2021). "A previous study demonstrated that modulation of C-X-C motif chemokine 11 (CXCL11) by MMPs might reduce the antitumor immune response and thus have direct consequences on tumor growth." (PMID 34038440, 2021). "In our model, mice treated with an antibody to block the binding of CXCL10 and CXCL11 to CXCR3 (but not the binding of CXCL9 to CXCR3) were unable to control the growth of established tumours." (PMID 33925140, 2021). "Notably, the CXCL9/CXCL10/CXCL11/CXCR3 axis recruits cytotoxic lymphocytes, NK cells, NKT cells, and macrophages to infiltrate tumor tissue and increases cytotoxic activity against tumor cells." (PMID 33763074, 2021). "CXCL11 also binds to CXCR7, implicating it in tumor invasiveness." (PMID 35087741, 2021). "The immune activation of IFN-γ on tumor cells is largely attributed to tumor cells, monocytes, endothelial cells, and fibroblasts inducing tumor cells to express MHC class I and secrete CXCL9, CXCL10, and CXCL11 to promote lymphocyte migration and inhibition of angiogenesis." (PMID 34795663, 2021). "In addition, we found that increased CXCL10, CXCL11, and CXCL13 expression increased survival in patients with OC with tumor progression." (PMID 34794429, 2021). "During inflammation, tumor infiltrating immune cells produce INF-γ, which in turn activates a variety of INF-γ-induced genes through the JAK/STAT pathway, such as CXCL9, CXCL10 and CXCL11." (PMID 34200459, 2021). "The expression of CXCL8, CXCL9, CXCL11, and CXCL13 was increased as the tumor stage increased." (PMID 33763130, 2021). "Moreover, the N-cadherin antagonist ADH-1 promotes the antitumor response of tumor infiltrating lymphocytes (TILs), interfering with the JAK/STAT pathway: CXCL11 and IRF1 were upregulated after using ADH-1." (PMID 34830179, 2021). "For example, effector immune cells, such as CD8 + Teff cells, IFN-γ-expressing T helper 1 (TH1) cells and natural killer (NK) cells, can be attracted to the tumor microenvironment by CXC-chemokine ligand 9 (CXCL9), CXCL10 and CXCL11, and exert potent antitumor effects." (PMID 34579759, 2021). "The CXCR7-mediated pro-metastatic responses may depend on CXCL11 or on higher receptors availability such as ER, EGFR or CXCR4 that significantly contribute to tumor growth and metastasis." (PMID 33937018, 2021). "Furthermore, EBV-encoded microRNAs (miRNAs) attenuate the attraction of cytotoxic T lymphocytes into the tumor microenvironment through downregulation of CXCL11 expression and inhibition of MHC I-restricted antigen presentation on the tumor cells." (PMID 33297336, 2020).
tumor (continued). "In this work, we identified that the expression of CXCL11 in HNSCC tissues was remarkably upregulated when compared with non-tumor tissue, and the mRNA levels of CXCL11 in patients with HNSCC were also significantly related to tumor stage." (PMID 33489879, 2020). "These variations, including those in GZMB, CXCL11, and NEIL3 suggest that the differences between patients from both races could be related to their immune response at the tumor niche." (PMID 32983990, 2020). "Our data demonstrate that the increase in T cell trafficking into poorly infiltrated tumors following TGFβ blockade may rely on tumor and/or tumor microenvironment expression of CXCR3 ligands: CXCL9, CXCL10, or CXCL11." (PMID 32273499, 2020). "Moreover, examination of cytokine/chemokine production in the tumor microenvironment revealed an increase in the levels of chemoattractive cytokines such as CCL3, CCL4, CCL5, CXCL9, CXCL10 and CXCL11." (PMID 32033490, 2020). "In fact, CXCR4, SPP1, ACKR3, CCL2, PTGS2, CD274 (PD-L1), CXCL11 were upregulated while CCL28, CCR1, CCR7 were down regulated in both comparisons (blue boxes), suggesting this as a signature specific of the core region of the tumor." (PMID 33066172, 2020). "Collectively, we speculate that, in the tumor microenvironment, TILRR can enhance immune infiltration by regulating the CXCL10 and CXCL11 chemokines." (PMID 33031059, 2020). "Furthermore, we analyzed the 50 highest TILRR-expressing and 50 lowest TILRR-expressing tumor tissue samples (TCGA database) to determine the relationship between the expression of CXCL10 and CXCL11 and the expression of TILRR in cancer tissues." (PMID 33031059, 2020). "The same group also developed a CXCL11/mesothelin CAR that increased intratumoral levels of CXCL11 but did not improve anti-tumor activity." (PMID 30804938, 2019). "For example, CXCL9 and CXCL10 induce effector Th1/Th17 cells and CXCL11 drives a Treg and Th2-biased effector cell polarization upon activation of CXCR3 on CD4+ T cells, while they upregulate tumor cell-related proteins that are beneficial for their survival, such as PD-L1." (PMID 31216755, 2019). "Intratumoral injection of interferon could increase the expression of CXCL-10, CXCL-11, and CCL5 in tumors and help lymphocytes to localize in tumor sites to perform antitumor activities." (PMID 31662753, 2019). "Functional experiments were carried out to check whether docetaxel (DOC), a chemotherapeutic agent, modifies the expression of HMGB1 and CXCL11, and influences the infiltration properties of CD8+ T cells to the tumor microenvironment." (PMID 30744691, 2019). "Collectively, these data suggest that the secretion of CXCL11 by tumor cells is induced by DOC rather than L-OHP." (PMID 30744691, 2019). "CCL19 and CXCL11 were not differentially secreted in the tumor (1221.47 ± 250 pg/ml and 69.1 ± 9 pg/ml, respectively) compared to the adjacent tissue (1399.5 ± 300 pg/ml and 34.6 ± 5 pg/ml, respectively)." (PMID 31105699, 2019). "One study employed a vaccinia virus to deliver the chemokine CXCL11 intratumorally in a subcutaneous mouse model of MPM and observed significantly increased levels of T cell infiltration and anti-tumor efficacy after intravenous mesothelin-directed CAR T cell injection." (PMID 30804938, 2019). "This occurred without implication of intratumoral chemokine expression because RNA‐seq analysis did not reveal reduced mRNA levels for CXCL‐9, CXCL‐10, and CXCL‐11 in bulk tumor tissue of male STAT1∆IEC mice (data not shown)." (PMID 29419930, 2018). "In comparison, CXCR3 gene was not upregulated in human OC tumor subtypes and no significant changes were observed in response to estrogen in OC cells, implying a positive effect mainly associated with the CXCR7/CXCL11 axis." (PMID 30051594, 2018).
tumor (continued). "Tumor upregulated chemokines included the followings: CXCL5 (138 fold increase); CCL25 (70 fold increase); CXCL11 (26 fold increase); CXCL6 (20 fold increase); CXCL1 and CXCL10 (11 fold increase); CXCL3 (8 fold increase); and CXCL9, CXCL2, and CCL3L1 (6 fold increase)." (PMID 29088818, 2017). "By using an oncolytic poxvirus that is designed to attract T cells with high efficiency (CXCL-11 expression) and upregulate PD-L1 (IFN-γ response to poxvirus infection as one of the mechanisms), the transformation of anti-PD-L1 resistant tumours into sensitive tumours is feasible." (PMID 28345650, 2017). "To test the effects of beta blockers on the chemokine environment in tumors of RRS-exposed animals, we examined the expression of genes that are characteristic of either immune suppression (Foxp3, CCL22) or effector anti-tumor immunity (Granzyme B, CCL5, IFN-γ, CXCL9, CXCL10 and CXCL11)." (PMID 28603578, 2017). "To further understand the role of adaptive immunity in the tumor tissue, we investigated the impact of RRS on tumor weight and on immune suppression markers (Foxp3, CCL22), as well as markers for anti-tumor immunity (Granzyme B, CCL5, IFN-γ, CXCL9, CXCL10 and CXCL11)." (PMID 28603578, 2017). "We have recently demonstrated in a poorly immunogenic (MC38 colon) tumour model, however, that an oncolytic vaccinia virus expressing the T-cell attracting chemokine, CXCL11, can attract effector cells into the TME and induce specific systemic anti-tumour immunity." (PMID 28345650, 2017). "Furthermore, αCD40 upregulated IL-2 and the Th1 T cell chemokines, CXCL10 and CXCL11, and increased CD8+ T cell infiltration and tumour PD-L1 expression." (PMID 26918344, 2016). "Moreover, tumor cells can produce both SDF-1/CXCL12 and ITAC/CXCL11, creating a complex signaling background and making experiments with exogenous chemokine ligand difficult to interpret." (PMID 23894550, 2013). "Notably, three genes in the classifier for the tumor stroma, CXCL10, CXCL11, and ISG20, are known interferon γ-regulated genes." (PMID 19225562, 2009). "The expression of CXCR3 receptors by CRC human tissues and by the human HT29 cells and the murine C26 tumour cells has led us to determine the ability of the corresponding ligands, CXCL9, CXCL10 and CXCL11 to affect the growth and chemotactic responses of HT29 and C26 cells in vitro." (PMID 19436305, 2009). "Consistently, lacidipine treatment or co‐administration with DOX/cisplatin significantly increased the mRNA expression of CCL5, CD274, CXCL10, and CXCL11 and decreased CCL2 mRNA levels in tumor tissues, thereby promoting immune cell infiltration and converting the “cold” into a “hot” tumor." (PMID 39585774, 2025). "Using isolated tumor tissue, we analyzed gene expression related to cytotoxicity (Perforin, Granzyme B, Granulysin, and FasL), inflammatory or chemotactic cytokines (IFN-γ, CXCL9, CXCL10, and CXCL11), and CD8+ T cell activation and proliferation (CD69, Tbx21, IL-2, and IL-12b)." (PMID 39066478, 2024). "In order to exclude the impact of EGF and CXCL11 on anlotinib-induced anti-migrating ability, we added rhCXCL11 and rhEGF to tumor cell with or without anlotinib treatment and found that invasion and migration of ATC cells could hardly be influenced." (PMID 37283515, 2023). "Quantitative PCR (qPCR) confirmed a significant increase of mRNA expression for the chemokine ligands Cxcl10 and Cxcl11, supporting our hypothesis that PARP14 inhibition enhances IFNγ signalling in tumour cells and upregulates immune cell infiltration into tumours." (PMID 37752135, 2023). "However, no marked infiltration of NK1.1-positive cells was observed in CXCL9- and CXCL11-expressing tumor tissues (data not shown)." (PMID 37218983, 2023).
tumor (continued). "Interestingly, synergistic effects of CXCL12 and CXCL11 on cell migration were only detectable in tumor cells in which CXCL11-dependent cell migration was sensitive to the p38 inhibitor, SB203580 (A549, A767), and in which CXCL11 and CXCL12 affected cell migration via different signaling pathways." (PMID 36539774, 2022). "Moreover, tumor tissues with a high T cell ratio within and close to the tumor nests in relation to the total stroma produced higher levels of CXCL9, CXCL10 and CXCL11, signifying the importance of the CXCR3-axis in T cell localization within the tumor microenvironment." (PMID 35954489, 2022). "However, the expression of CXCL11 was not significantly different between different tumor stages in the remaining cancers." (PMID 35935945, 2022). "One well-documented example is that patients with high CXCL11 expression tend to possess a high abundance of intra-tumor CD8+ T cells and CD56+ NK cell infiltration in the tumor, and those cells are correlated with the anti-tumor immune response, resulting in a favorable prognosis." (PMID 36589745, 2022). "CCR5-CCL4/CCL5 and CXCR3-CXCL9/CXCL10/CXCL11/CXCL13 axis were significantly correlated with CD 4 T and CD 8 T cells, indicating that these chemokine–receptor pairs may recruit the T lymphocytes into tumor." (PMID 35530341, 2022). "These include plasmid-borne CXCL9, intra-tumor injection of CXCL9, recombinant CXCL10 protein with adoptive cell therapy (ACT), intra-tumor injection of CXCL10, retroviral transduction tumor cells with CXCL10, and intraperitoneal injection of oncolytic vaccinia virus expressing CXCL11." (PMID 33603130, 2022). "Moreover, in none of the tumor cells, gelatinase expression was affected by CXCL12 and/or CXCL11, implying that gelatinases do not account for co-operative effects of these chemokines on tumor cell invasion." (PMID 36539774, 2022). "In summary, our work suggests a mechanism whereby CXCL11 acts as a key mediator integrating CAFs and CAF-cohabitating cancer cells, and functions as an extracellular remodeler promoting HCC migration and metastasis through the activation of circUBAP2/miR-4756/IFIT1/3 in tumor cells." (PMID 33707417, 2021). "Other chemokines upregulated in either the tumour or infiltrating immune cells by CHK1i+LDHU, including CCL5 that directly recruits Tregs or CXCL9, CXCL10, CXCL11 that recruit activated effector, T, NK and NKT cells, as well as Tregs, may also be responsible for the accumulation of Tregs." (PMID 34359633, 2021). "Although this mechanism contributes to the suppression of tumor progression, it may be offset by the inhibition of the angiostatic cytokines CXCL9, CXCL10, and CXCL11; this can promote, in addition to tumor neovascularization, tumor growth or metastasis formation." (PMID 34442627, 2021). "Therefore, we determined that the IHC results of CXCL11 were either positive or negative according to its expression in the cytoplasm of tumor cells." (PMID 33547412, 2021). "While all three CXCR3 ligands were elevated in niches with actively growing tumor populations, IP-10 (CXCL10; growing 2.2-fold, emergent 1.5-fold) was present at markedly higher absolute levels than that of MIG (CXCL9; growing 1.5-fold, emergent 1.4-fold) and I-TAC (CXCL11; emergent 1.4-fold)." (PMID 34123844, 2021). "A recent review reports that the CXCL9/CXCL10/CXCL11/CXCR3 axis is responsible for angiogenesis inhibition, and the activation and migration of immune cells such as cytotoxic lymphocytes and natural killer cells into the tumor microenvironment, to prevent tumor progression in BCa." (PMID 33003392, 2020). "Our results demonstrate that DOC induces CD8+ T cell recruitment to the tumor microenvironment by enhancing the secretion of HMGB1 and CXCL11, thus improving the anti-tumor efficacy, indicating that modulating the HMGB1-CXCL11 axis might be helpful for NSCLC treatment." (PMID 30744691, 2019).
tumor (continued). "Pathways involving tumor-expressed extracellular membrane-bound chemokines CXCL9, CXCL10, and CXCL11 were identified and show potential interactions in networks translating intracellular damage to extracellular signals that may stimulate immune recruitment and tumor cell death." (PMID 25952672, 2015). "Furthermore, CCR5-CCL4/CCL5 and CXCR3- CXCL9/CXCL10/CXCL11/CXCL13 axis were significantly correlated with CD 4 T and CD 8 T cells, indicating that these interactions may be essential for the recruitment of the T lymphocytes into tumor." (PMID 35530341, 2022). "Since synergistic effects of CXCL12 and CXCL11 on tumor cell migration do not correlate with the selective use of distinct chemokine receptors / receptor combinations, we asked whether additive effects would correlate with receptor-activated signaling pathways." (PMID 36539774, 2022). "In addition, accumulating evidence has suggested that the CXCL10 and CXCL11/CXCR3 axis could impose antitumor effects by recruiting Th1 cells, cytotoxic T cells, natural killer cells, and natural killer T cells to tumor sites and it has protumor effects on cancer cells expressing CXCR3." (PMID 36003333, 2022). "CCL5 was found to be remarkably elevated in tumor tissues collected from PTC patients coexistent with HT than those without HT, and CXCL9, CXCL10, CXCL11, and CXCL13 were also reportedly upregulated in thyroid tissues from HT patients." (PMID 38137348, 2023). "Although higher expression of VEGF was observed in tumor tissues transplanted with parental SCCVII cells, no significant suppression of VEGF expression was observed in CXCL9- and CXCL11-expressing tumor tissues (data not shown)." (PMID 37218983, 2023). "We further found that tumor-rich tissues produced higher levels of CXCL9, CXCL10 and CXCL11 compared to nontumor tissues." (PMID 35954489, 2022). "qRT-PCR showed that L. paracasei sh2020 made a drastic increase in the level of CXCL10 in tumor tissue, whereas no changes were found in CXCL9, and CXCL11." (PMID 35259052, 2022). "A transcriptomic analysis of human tumor liver tissue showed an increased expression of several chemokines, such as CCL20, CXCL10, and CXCL11, compared with adjacent non-tumor liver tissue." (PMID 35008212, 2021). "Although binding affinity of CXCL11 to CXCR7 is low, but it can induce intracellular signaling in CXCR3-negative tumor and non-tumor cells." (PMID 34298991, 2021). "On the contrary, CXCL4, CXCL9, CXCL10, CXCL11, CXCL12, CXCL13, and CXCL14, lacking the ELR amino acid motif (ELR−), can inhibit tumor angiogenesis." (PMID 34497764, 2021). "Immunohistochemistry was performed to verify that there was a higher expression of CXCL11 protein in lung cancer tumor sites from patients treated with DOC combined with L-OHP, compared to tumor sites derived from patients who did not undergo chemotherapy." (PMID 30744691, 2019). "For example, the tumor supernatants contained low levels of CXCL9, CXCL10 and CXCL11 (data not shown) that bind to CXCR3, a chemokine receptor known to be upregulated on NK cells upon activation and expansion." (PMID 28923105, 2017). "The atypical chemokine receptor 3 (ACKR3), which does not couple to G-proteins and does not mediate cell migration, acts as a scavenger for CXCL11 and CXCL12, interfering with the tumor homing CXCL12/CXCR4 axis." (PMID 29156704, 2017). "The tumor evasion from CXCR3+ cells is probably not dependent on chemokine production by the tumor since CXCR3 ligands CXCL10 and CXCL11 both are present in higher concentrations in the tumor." (PMID 22319577, 2012). "As for the murine cells, the chemotactic responses towards various concentrations of chemokines were tested and confirmed the migratory ability of the human tumour cells in response to two of the three ligands (CXCL9, CXCL10 but not CXCL11)." (PMID 19436305, 2009).